EGF (epidermal growth factor)
Diseases named in the same sentence as EGF in open-access papers (continued):
Sharing a sentence is not in itself a finding about the gene and the disease.
glioblastoma (continued). "In a similar manner, AuNPs functionalized with epidermal growth factor or transferrin receptors were loaded with the photosensitizer silicon phthalocyanine (Pc 4) and then employed in photodynamic therapy of glioblastoma." (PMID 35054340, 2022). "This functional link between S1P and EGF signalling pathways has already been described in human glioblastoma multiforme cell lines." (PMID 35806446, 2022). "In the glioblastoma, Rab27b mediates the secretion of Epiregulin, which is a membrane protein of the epidermal growth factor (EGF) family, to promote cell proliferation after irradiation treatment in paracrine effects." (PMID 35927755, 2022). "Here, we characterize a unique subgroup of CSCs in MGMT-null experimental glioblastoma, identifying EGF + TMZ therapy as a potential strategy to overcome cellular quiescence and TMZ resistance, likely endowed by deficient EGFR signaling." (PMID 36316307, 2022). "Other factors, such as TGFβ, TNFα, IL6, HGF, EGF, and PDGF are also regulators and inducers of EMT and are all implicated in glioblastomas." (PMID 35053605, 2022). "It has been reported that EGF-mediated ERK1/2 activation stimulated PKM2 phosphorylation at serine 37 in glioblastomas." (PMID 35931120, 2022). "Generally, the literature defines EGF and TGFβ as proneoplastic at advanced stages of glioblastoma tumorigenesis." (PMID 36292985, 2022). "In our study, LH-EGFR signaling-activated SphK1/2 in granulosa cells to increase S1P levels, consistent with a previous study showing that EGF enhances S1P synthesis and secretion in glioblastoma stem cells." (PMID 36396932, 2022). "The present study attempts to determine the role of TGFβ and EGF in glioblastoma EGFRvIII-positive cells based on three DK-MG sublines with different EGFRvIII expression status: DK-MGlow, DK-MGhigh, and DK-MGextra-high." (PMID 36292985, 2022). "Luteolin inhibits the mitogen-activated protein kinase (MAPK) signaling pathway of the downstream signaling pathway of epidermal growth factor, thereby inhibiting the proliferation of glioblastoma." (PMID 33935785, 2021). "WTAP is over-expressed in the glioblastoma stem cells, controlling the invasion of glioblastoma cells via regulating epidermal growth factor (EGF) signaling." (PMID 33664770, 2021). "In support of that, the specific cleavage of GRP78 in glioblastoma cells (U251 line) treated with the fusion protein epidermal growth factor (EGF)-SubA increased the cancer cell sensitivity to both temozolomide and ionizing radiation." (PMID 33806538, 2021). "Briefly, in a hypoxic microenvironment the HIF1α/HIF2α-miR210-3p network promotes the malignant progression of glioblastoma through a positive feedback loop with EGF." (PMID 33208727, 2020). "The effects of EGF on the invasiveness of human glioblastoma T98G cells were estimated using time-lapse video microscopy, immunocytochemistry, cell cycle assay, immunoblot analyses, and Transwell® assay." (PMID 32443749, 2020). "As a result, inhibition of the EGF stimulation of VEGF production by human malignant GBM cells is well established as a model of glioblastoma multiforme pathophysiology." (PMID 31698752, 2019). "We have successfully applied this model to identify the interconnections altered in the constitutive signaling of the mutated EGFR by comparing EGF-dependent and wild-type EGFR signaling in glioblastoma multiforme." (PMID 31386654, 2019). "To this end, we enriched cancer stem-like cell populations in U373 glioblastoma by maintaining cells with serum-free culture media supplemented with 20 ng/mL epidermal growth factor (EGF) and basic fibroblast growth factor (bFGF)." (PMID 30388862, 2018). "To further understand the downstream pathway and biological functions of EGF signaling in glioblastoma, we extracted single-cell RNA sequencing (scRNAseq) data of grade IV glioblastoma." (PMID 30514230, 2018).
glioblastoma (continued). "This idea is consistent with the report showing that SP1 is required for the EGF-induced expression of Arf6 mRNA in the human glioblastoma cell line U87 cells." (PMID 28429746, 2017). "Microglia synthesize and release stress-inducible protein 1 (STI1), a cellular prion protein ligand that increases the proliferation and migration of glioblastomas in vitro and in vivo, as well as EGF, which stimulates glioblastoma cell invasion." (PMID 29410971, 2017). "To evaluate the effect of QUE on GSCs, we first isolated cells from the glioblastoma cell line GL261 to form spheres in a serum-free conditional medium with EGF and bFGF." (PMID 28415586, 2017). "EGF through its receptor (EGFR), which is frequently overexpressed in glioblastomas, promotes the transcription of genes associated with the extracellular matrix proteolysis such as matrix metalloproteases 2 and 9 (MMP-2 and 9)." (PMID 28168193, 2017). "Stimulation of EGFRvIII-positive glioblastoma derived neurospheres with EGF produced variable results, whilst U87-MG cells expressing EGFRvIII (same model as in the literature report) did not respond to the stimulus." (PMID 27004406, 2016). "In later stages of tumor progression, MG are able to stimulate glioblastoma cell invasion via EGF or MT1-MMP secretion." (PMID 27936099, 2016). "Activation of the ELK1 led to increased survival and proliferation following EGF stimulation in the U138 glioblastoma cells." (PMID 27884160, 2016). "Other Rho-family GTPases have not yet been examined, but RhoG merits consideration since it has been reported to stimulate membrane ruffling and macropinocyctosis and can activate Rac1 in response to EGF or HGF in glioblastoma cells." (PMID 25762935, 2015). "At that later stage, microglia are able to stimulate glioblastoma cell invasion via epidermal growth factor (EGF) secretion." (PMID 24723924, 2014). "Although ΔEGFR is unable to bind to EGF, it is still constitutively phosphorylated and activates downstream signaling cascades, and promotes the survival and proliferation of glioblastoma cells." (PMID 27408849, 2013). "A recent study confirmed that the PKM2 induced by epidermal growth factor (EGF) translocates into the nucleus of glioblastoma cells, interacts with β-catenin and leads to cyclinD1 expression, which promotes cell proliferation and tumorigenesis." (PMID 23840737, 2013). "KCa3.1 channel inhibitors were in fact ineffective in modulating the chemotactic response to epidermal growth factor (EGF), another physiologically relevant chemotactic inducer in glioblastoma." (PMID 22675627, 2012). "A recent study has found that Arf6 is required for EGF-induced glioblastoma cell proliferation via the activation of PI3K and ERK signaling." (PMID 22701712, 2012). "To determine the role GRP78 plays in glioblastoma tumorigenesis, we explored the anti-tumor activity of the novel fusion protein EGF-SubA, which combines EGF with the cytotoxin SubA that has been recently shown to selectively cleave GRP78." (PMID 23284962, 2012). "It has also been shown that transplantation of neurospheres derived from glioblastoma tumor cells cultured in EGF and bFGF-containing media drove tumor formation in immune-deficient mouse models." (PMID 22995409, 2012). "Our results indicate that this novel EGF effector identified from glioblastoma initiating cells behaved in a cell-type dependent manner." (PMID 22912867, 2012). "EGF-SubA demonstrated potent tumor-specific proteolytic activity and cytotoxicity in glioblastoma lines and potentiated the anti-tumor activity of both temozolomide and ionizing radiation." (PMID 23284962, 2012). "In a preliminary study of GSCs, we compared the growth properties of human glioblastoma cell lines U87, T98, U138, D54 and LN-229 in serum-free medium supplemented with EGF and bFGF." (PMID 22330721, 2012).
glioblastoma (continued). "As amplification or mutation of EGF receptor frequently occurs in glioblastoma tumors, aberrant EGF signaling is considered to make a substantial contribution to malignant character of glioblastoma stem cells." (PMID 22912867, 2012). "As it is well-known that amplification of EGF receptor frequently occurs in glioblastoma tumors, elevated EGF signaling is considered to make a substantial contribution to malignant character of glioblastoma stem cells." (PMID 22912867, 2012). "Here, we show that depletion of RhoG significantly inhibits both HGF- and EGF-stimulated Rac1 activation in glioblastoma cells, demonstrating that RhoG acts upstream of Rac1 in these cells." (PMID 22966858, 2012). "In order to investigate EGF-induced signaling alteration at the network level, we performed global phosphoproteome analyses of SILAC-encoded glioblastoma initiating cells using high-resolution nanoflow LC-MS/MS system." (PMID 22912867, 2012). "High expression of EGF had been detected in some cancer tissues, such as gallbladder cancer and glioblastoma." (PMID 20487573, 2010). "We show here that SNAI2/Slug is overexpressed in a subpopulation of glioblastomas in an EGF-dependent manner, and SNAI2/Slug mRNA expression correlates with increasing tumor grade and invasive phenotype in human gliomas." (PMID 20565806, 2010). "We observed a significant increase in SNAI2 mRNA and protein in U251 glioblastoma cells after EGF exposure." (PMID 20565806, 2010). "We found that in vitro culture of human glioblastoma cells with EGF+bFGF induced the generation of gliospheres with more than 50% of cells positive for CD133, suggesting the successful expansion of BTSCs in culture." (PMID 19018263, 2008). "In this study, we generated gliospheres with more than 50% CD133+ BTSC by culturing U87MG and T98G human glioblastoma cells with epidermal growth factor (EGF) and basic fibroblast growth factor (bFGF)." (PMID 19018263, 2008). "For instance, for brain cancer and glioblastoma models, epidermal growth factor (EGF), basic fibroblast growth factor (bFGF) or insulin-like growth factor (IGF) are used along with neurobasal medium supplemented with B27 or N2 to replicate brain tumor signaling and support neural cell growth." (PMID 40718488, 2025). "Similarly, EGF stimulates GLUT1 protein expression in glioblastoma cells, and promotes GLUT4 translocation to the plasma membrane in HeLa cells." (PMID 39433211, 2025). "In contrast, EGF exhibited significant differential expression in a more limited subset of cancers, specifically esophageal carcinoma, glioblastoma multiforme, liver hepatocellular carcinoma, lung adenocarcinoma (LUAD), lung squamous cell carcinoma, and pancreatic adenocarcinoma." (PMID 40692603, 2025). "Recent studies have demonstrated that harmine exhibits promising anti-glioblastoma effects through various mechanisms, including the inhibition of glioblastoma cell proliferation and migration, as well as the blockade of EGF-mediated phosphorylation of FAK/AKT." (PMID 40286187, 2025). "IDH with other targeted gene mutations explored recently in glioblastomas such as telomerase reverse transcriptase (TERT) mutation, epidermal growth factor (EGF) amplification, or chromosomal 10 or 7 gain/loss can be tested using next-generation sequencing (NGS) from the resected tissue." (PMID 37525780, 2023). "A similar result was earlier reported when fibroblast and glioblastoma cells were treated with EGF." (PMID 37095445, 2023). "EGF is known to promote cell motility in glioblastoma, like in many other cancers." (PMID 36766769, 2023). "Thus, proliferation of U87MG was assessed in response to treatment with EGF (10 ng/mL), which plays an essential role in glioblastoma metastasis, and VEGF (10 ng/mL), which acts as a major angiogenic factor." (PMID 37723574, 2023).
glioblastoma (continued). "In addition, because the activation of the EGFR pathway has been previously linked to altered metabolic processes, including the “lipogenic phenotype” in glioblastoma multiforme, we investigated the effect of EGF treatment in these cells." (PMID 36732018, 2023). "Furthermore, we discovered that endogenous Spastin is directed to actins in T98G glioblastoma cells upon Pin1 overexpression, which is comparable to EGF treatment." (PMID 36766769, 2023). "A differential effect of EGF on EGFRvIII-positive glioblastoma cells was observed." (PMID 36292985, 2022). "Since expression and nuclear localisation of PKM2 is regulated by epidermal growth factor (EGF) in U87 human glioblastoma cells, we tested the effects of EGF and also basic fibroblast growth factor (bFGF), a clinically important growth factor in CRCs, on PKM2 expression in CRC cells." (PMID 33071283, 2021). "Moreover, GBP1 is induced by EGFR signaling and promotes invasion because it is required for the EGF-induction of MMP1 in glioblastoma." (PMID 34439200, 2021). "In addition, TF expression in glioblastoma cells mediated by EGFR overexpression or EGF stimulation was JNK1 dependent." (PMID 34205482, 2021). "Because TAT-Cx43266–283 inhibits NPC growth promoted by EGF and FGF-2 via Src inhibition, this peptide might be used to target NPCs carrying mutations that lead to glioblastoma development." (PMID 33238452, 2020). "We treated glioblastoma cells with EGF extrinsically and found that SIX3 was downregulated." (PMID 32051553, 2020). "Moreover, it is known that EGF plays a role in the metastasis of glioblastoma by induction of matrix metalloproteinase-9 in an EGFR-dependent mechanism." (PMID 29584702, 2018). "As ADAM10 and ADAM17 are overexpressed in glioblastoma where they can act to increase the EGF concentration in the niche then anti-ADAM10 and ADAM17 treatment may mediate migration out of the niche by reducing local EGF concentrations." (PMID 27541285, 2017). "Created by co-culturing GBM cells with cerebral organoids, GLICOs involve embedding organoids in Matrigel and co-culturing with glioblastoma stem cells in a medium containing EGF, bFGF, and heparin." (PMID 40647519, 2025). "It was demonstrated that synergistic use of OV-IL15C plus epidermal growth factor (EGFR)-CAR NK cells was able to suppress glioblastoma (GBM) cells and also enhanced the infiltration of NK and CD8+ T cells." (PMID 36434591, 2022). "The epidermal growth factor (EGFR) receptor is frequently overexpressed in glioblastoma multiforme IV (GBM)." (PMID 36199696, 2022). "Similarly to TGFβ, EGF also plays an important role in glioblastoma biology." (PMID 36292985, 2022). "This indicates that transcriptome changes in the process of glioblastoma NS formation are determined to a greater extent by the initial cell-specific context of gene expression, but strongly modulated by the conditions of cultivation in the presence of bFGF and EGF." (PMID 36354672, 2022). "NHE9 is also highly expressed in glioblastoma multiforme (GBM), the most common brain tumour, as endolysosomal pH is critical for epidermal growth factor (EGFR) sorting and turnover." (PMID 33118634, 2020). "Thus we investigated whether protein molecules encoded by previously undefined regions in the human transcriptome were involved in the phosphoproteome dynamics in EGF signaling of human glioblastoma initiating cells." (PMID 22912867, 2012). "At the same time, Valproic Acid, Cadmium, Pulmonary Fibrosis, Glioblastoma, IGF2BP3, Curcumin, Cisplatin, Cyclosporine, Quercetin, and Tretinoin show an interaction relationship centred on EGF." (PMID 40461634, 2025). "A closer analysis of the potential signaling pathways involved in reducing cell viability reveals the downregulation of EGF-induced FAK, AKT, and GSK3ß in glioblastoma cells." (PMID 40422257, 2025). "On the other hand, TAMs can secrete EGF, which stimulates EGFR in glioblastoma cells, thereby reinforcing the oncogenic circuit." (PMID 38515213, 2024).
glioblastoma (continued). "Through functional enrichment analysis, we identified the following pathways MAPK, EGF/EGFR, Ras, EGFR, PI3K-AKT signaling, MAPK signaling, Glioblastoma signaling, pathways as a common target for miR-21, miR-374, and miR-126." (PMID 39348350, 2024). "The situation is further complicated by the fact that several distinct growth factors have been identified as autocrine signals in glioblastoma, e.g. TGF-α and EGF." (PMID 35239640, 2022). "For example, higher invasion was observed when glioblastoma cells expressed EGFR and responded to EGF secretion from microglia." (PMID 35053605, 2022). "EGF or HRG have been reported to promote CXCR4 serine and/or tyrosine phosphorylation in glioblastoma or BC cells leading to CXCL12-independent receptor activation of downstream cascades." (PMID 36233192, 2022). "Activated microglia release interleukin IL-6 and relevant growth factors, including epidermal growth factor (EGF), vascular endothelial growth factor (VEGF), and transforming growth factor-β (TGF-β), which stimulate glioblastoma cell invasion and angiogenesis." (PMID 35885058, 2022). "In glioblastoma (GBM), stimulation of the cells with EGF induced MEK- and RSK-dependent EphA2 S897 phosphorylation." (PMID 33572284, 2021). "Some microglia-derived soluble proteins, such as stress-inducible protein 1 (STI 1), epidermal growth factor (EGF), and transforming growth factor-β (TGF-β), were found to participate actively in glioblastoma progression." (PMID 34439380, 2021). "Subsequent culture of C6 cells as neurospheres (glioblastoma stem-like cells, GBSC) suspended in DME/F12 medium supplemented with EGF, bFGF, and B27 supplement also indicated DCX expression." (PMID 32050972, 2020). "To investigate the function of ZNF263 and SIX3 in the context of glioblastoma development, we first treated the phenotypically normal astrocytes (HEB cells) with high doses of EGF to mimic EGFR/MAPK hyperactivation during tumor initiation." (PMID 32051553, 2020). "In human glioblastoma multiforme, PKM2 acts as a nuclear coactivator during EGF-induced β-catenin transactivation, and PKM2 binds to c-Srcphosphorylated Y333 of β-catenin." (PMID 32096765, 2020). "A recent report provides evidence to indicate CD109 enhances EGF signaling while attenuating TGF-β signaling, in SK-MG1 glioblastoma cells." (PMID 31695056, 2019). "Epidermal growth factor (EGF) and EGF receptor (EGFR) play prominent roles in the metastasis of glioblastoma (GBM)." (PMID 29029486, 2017). "In particular, the invasive capabilities of LN428, LN308 and LN229 lines increased by 3.5- to 5-fold upon EGF stimulation, consistent with the strong pro-malignant function of EGFR in glioblastomas." (PMID 26377974, 2015). "Recently, a study reported about an EGF-enhanced VCAM-1 expression promoting macrophage and glioblastoma cell interaction and tumor cell invasion." (PMID 25030093, 2014). "In search of a mechanism for the contribution of RhoG to the malignant behavior of glioblastoma cells, we found that depletion of RhoG strongly inhibits activation of the Rac1 GTPase by both HGF and EGF." (PMID 22966858, 2012). "Initial discovery and extensive studies of the epidermal growth factor (EGF) and transforming growth factor alpha (TGF-α), as well as the platelet-derived growth factor (PDGF) family, revealed their presence in glioblastoma cell cultures and tissues." (PMID 22509804, 2012). "As epidermal growth factor (EGF) is a key player in neoplastic progression and AKT is a key effector of EGFR signalling, we analyzed EGFR levels in glioblastoma treated with PF4-DLR." (PMID 21060779, 2010). "In the process of acquiring the M2 phenotype, GAMs secrete immunomodulatory and tumor-promoting factors such as TGF-β, epidermal growth factor (EGF), IL-10, and the proteolytic enzymes MMP-2 and MMP-9, thereby reinforcing an immunosuppressive tumor milieu within the glioblastoma microenvironment." (PMID 41479886, 2025).